INS (insulin)
Diseases named in the same sentence as INS in open-access papers (continued):
Sharing a sentence is not in itself a finding about the gene and the disease.
Obesity (continued). "Consistent with reduced obesity, HFD‐fed Cxxc5−/− mice exhibited markedly improved glucose tolerance and insulin sensitivity, with improved levels of metabolic parameters, including leptin, resistin, adiponectin, TGs, total cholesterol and HDL‐cholesterol levels." (PMID 35384342, 2022). "Indeed, decreased insulin sensitivity, attributable to a post-receptor binding defect in the insulin signaling pathways, has been identified as an intrinsic component of PCOS, independently of obesity." (PMID 36139396, 2022). "The increase in circulating levels of DPP-4 occurring during obesity could determine a pronounced inactivation of endogenous GLP-1, thus reducing the insulinotropic action of GLP-1 and consequently insulin secretion." (PMID 35628332, 2022). "We do not yet understand the relative importance of insulin clearance mechanisms in the pathogenesis of obesity or other metabolic diseases." (PMID 35163746, 2022). "Without differences in obesity and/or abdominal obesity and to a lesser extent systemic inflammation, the connection between insulin resistance and biological aging appears to be minimal." (PMID 35586815, 2022). "In addition, fasting insulin and HOMA-IR were significantly higher in hypothyroid children with obesity compared to lean hypothyroid children (P < 0.001)." (PMID 35501770, 2022). "It was used as adjunct therapy to insulin by 26.3% of our patients with overweight/obesity, mainly females (data not shown)." (PMID 34983637, 2022). "In contrast, the myocyte-specific deletion of CerS5 and CerS6 did not affect insulin sensitivity and glucose metabolism in obesity, highlighting the tissue-specific regulation and roles of distinct CerSs and their specific ceramide products." (PMID 35789435, 2022). "GPR43 knockout mice display weight gain, increased adiposity, and reduced systemic insulin sensitivity even on a normal chow diet, whereas adipose tissue‐specific GPR43 overexpression protects mice against the development of obesity even when a HFD is consumed." (PMID 35856338, 2022). "Similar to the diet-induced obesity experiment, we also did not observe changes in insulin sensitivity." (PMID 35802167, 2022). "Surprisingly, deleting CerS1 in skeletal muscle to reduce C18:0 ceramide synthesis in obesity did not appreciably affect muscle-specific insulin signaling or glucose uptake." (PMID 35789435, 2022). "We are enrolling 100 persons 18–45 years of age within 6 years’ T2DM diagnosis, not on insulin therapy, and with obesity." (PMID 36130753, 2022). "Insulin tolerance improved to about the sensitivities of controls that were not exposed to diet-induced obesity." (PMID 35458115, 2022). "During hibernation, brown bears experience periods of insulin resistance, physical inactivity, extreme bradycardia, obesity, and the absence of urine production." (PMID 35100340, 2022). "The deterioration in glycemic control observed in people with obesity and both IFG and IGT or T2D is caused by a marked decrease in the β cell response to plasma glucose (i.e., GSIS), not a decrease in insulin sensitivity." (PMID 34905513, 2022). "Body weight reduction due to hypocaloric diets normalized hyperglycemia by improving ß-cell function as well as hepatic IR in subjects having obesity and T2DM and also improved IR in skeletal muscle in young, lean, insulin-resistant subjects by promoting insulin-stimulated muscle glucose uptake." (PMID 35314768, 2022). "Here the authors report a randomized controlled trial to compare the effects of eTRF and mTRF in healthy volunteers without obesity, and find that eTRF is more effective in improving the primary outcome insulin sensitivity." (PMID 35194047, 2022). "A mildly insulin resistant individual will have obesity with or without hyperglycemia, but elevated insulin concentrations in the basal and postprandial state." (PMID 35244142, 2022).
Obesity (continued). "Conversely, an obesity-related hypo-dopaminergic state, allowed for measurable improvements in insulin sensitivity regardless of timing of bromocriptine administration." (PMID 35711802, 2022). "An anti-MIF antibody and the absence of MIF inhibited glucose-stimulated insulin release resulting in the development of obesity, glucose intolerance and hyperglycemia." (PMID 35091838, 2022). "In models of high fat–induced obesity, adipocyte COX-2 expression was reported to increase, and administration of selective COX-2 inhibitors or global COX-2 gene deletion reduced adipose tissue mass and inflammation and skeletal muscle insulin resistance." (PMID 35499079, 2022). "Muscle is the main target tissue for insulin in glucose metabolism, while in obesity, it can use non-esterified fatty acids (NEFAs) as an energy substrate." (PMID 35884769, 2022). "Individuals living with obesity had significantly greater BMI, % body fat, body fat mass (kg), waist and hip circumference, and higher blood concentrations of TG, total cholesterol, LDL-C, glucose, and insulin in comparison with normal weight individuals." (PMID 35247847, 2022). "We hypothesized a stronger insulin effect on FCR in participants with normal weight compared to participants with overweight and obesity in brain regions involved in eating behavior." (PMID 35715625, 2022). "Moreover, the latest evidence suggests a significant improvement in glycemic control and obesity with tirzepatide compared to placebo, GLP1 receptor agonists, and insulin." (PMID 36362984, 2022). "In the majority of these studies, the degree of obesity and not the direct measurement of insulin resistance was used to identify individuals as insulin resistant vs. insulin sensitive." (PMID 35681299, 2022). "Patients with obesity had significantly higher homeostasis model assessment (HOMA-IR) and lower whole body insulin sensitivity index (WBISI) (p < 0.001) compared to patients without obesity." (PMID 35842601, 2022). "Taken together, our study using HFD-induced obesity animal model shows that MSDC-0602K, as a novel insulin sensitizer, has reduced detrimental effects on bone parameters and BM-MSC phenotype by activation of glutamine metabolism as compared to the first generation of TZDs, i.e. pioglitazone." (PMID 36103974, 2022). "It has been well documented that women with PCOS, independent of obesity, are insulin-resistant and have compensatory hyperinsulinemia." (PMID 35646061, 2022). "If insulin treatment reaches the established blood glucose control level, the risk of PE in GDM with obesity is not different from that in normal weight." (PMID 35252402, 2022). "In this secondary analysis, we investigated the relationships between serum miRNA profile, metabolic biomarkers (insulin, lipid profile, adipokines, and liver enzymes), and IHTG percent in a well-described cohort of pubertal children with obesity and varying degrees of IR." (PMID 35498403, 2022). "Students with overweight and obesity had higher WC, body fat mass, blood pressure levels, glycemic levels (fasting glucose, insulin levels, HOMA-IR), TC, TG, LDL-C and lower HDL-C than non-OB group." (PMID 35305598, 2022). "In the present study, we aim to determine the associations between circulating miRNAs and metabolic and hepatic features of NAFLD and serum levels of insulin, adiponectin, and fibroblast growth factor (FGF)-21 in children with obesity and varying degrees of IR and intrahepatic triglyceride (IHTG)." (PMID 35498403, 2022).
Obesity (continued). "In healthy humans, insulin increased coronary flow reserve by ~20–26%, an effect which was maintained in young T1DM patients without microvascular complications or autonomic neuropathy but blunted in patients with obesity or T2DM and in acute insulin-resistant states induced by lipid infusion." (PMID 36140374, 2022). "This is the first multimodal study to investigate the acute effects of IN insulin on palatable food intake and hunger in satiated women with and without obesity." (PMID 35397638, 2022). "Chlorogenic acid could exert anti-diabetic and anti-obesity effects through the AMPK pathway, enhance the expression levels of PPARγ, PRDM16, and PGC-1α in BATs and WATs, increase the insulin production, and inhibit key enzymes in lipid biosynthesis." (PMID 35886989, 2022). "We sought to support our hypothesis with a comprehensive assessment of the effects of obesity on atrial gene expression and found multiple SGK1-related pathways to be upregulated, including insulin and mineralocorticoid signaling." (PMID 35998035, 2022). "In this study, we investigated the genetic overlap of AD, ASD, OCD with somatic insulinopathies, namely MetS, obesity and T2DM, hypothesising an important role for gene sets related to insulin signalling." (PMID 35165256, 2022). "This is not unexpected because T2D is primarily due to severe β-cell dysfunction whereas insulin sensitivity is no worse than in people with obesity without T2D." (PMID 35054781, 2022). "Patients who developed AD had an overall higher incidence of comorbidities but surprisingly, had a significantly lower incidence of obesity in both metformin and insulin populations compared to patients who did not develop AD." (PMID 35601622, 2022). "At the same time, the chance of having an unstable plaque decreased with an increase in insulin by 3% in patients without obesity." (PMID 36013196, 2022). "GLP-1 was positively correlated with insulin, HOMA-IR, and obesity-markers except percent body fat." (PMID 36355134, 2022). "The diet-induced obesity (DIO) model is widely used in rodents as it recapitulates numerous features of human obesity, including a progressive weight gain involving expansion of visceral adipose tissue and whole body insulin resistance." (PMID 35657616, 2022). "However, the estimates for insulin/insulin analogues and GLP-1 analogues were varying across the 3 obesity-related traits." (PMID 35654594, 2022). "Intranasal insulin increased working memory RT of women with obesity but had no other effect on cognitive measures for either BMI group." (PMID 35397638, 2022). "In this review, we concentrate on tumors positively correlated with obesity, and the role of insulin in driving tumor progression, while recognizing that no monolith regarding the relationship between metabolism and cancer exists." (PMID 35244142, 2022). "Initially, we investigated a middle-aged cohort of C57BL/6NTac mice that had been on high-fat diet their entire life, however, the results showed that PT did not improve obesity, glucose tolerance or insulin sensitivity." (PMID 36145121, 2022). "Previously, the best independent predictive risk factor for diagnosing NAFLD in non-diabetic children with obesity was suggested to be fasting insulin >18.9 μIU/ml." (PMID 35185803, 2022). "The insulin sparing action of E4 can reduce high levels of circulating endogenous insulin and improve the glycemic control by activating the distal insulin signaling pathway independent of obesity, thereby improving NAFLD." (PMID 36012550, 2022). "Similarly, the obesity phenotypes in D. melanogaster induced by HSD and HFD feeding are accompanied by increased fat storage, alterations in carbohydrate-insulin homeostasis, and reductions in fitness and reproductive capacity." (PMID 35204721, 2022). "Finally, Selenoprotein P impairs insulin signaling and glucose homeostasis and is considered a biomarker for T2DM, obesity and NAFLD." (PMID 35740032, 2022).
Obesity (continued). "Insulin levels and the insulin AUC during the OGTT were significantly increased in obese β-Xbp1+/+Ob mice compared with lean β-Xbp1+/+Wt mice, characteristic of the beta cell compensatory response to obesity." (PMID 35316840, 2022). "In the regression model, onset of overweight/obesity did not contribute significantly to the variations between subjects in insulin or HDL-cholesterol." (PMID 35228658, 2022). "However, patients who developed AD after being exposed to insulin had a higher incidence of COPD, chronic kidney disease, chronic heart failure, coronary artery disease, obesity and stroke but had less incidence of hypertension." (PMID 35601622, 2022). "One of the most prominent associations in mice and human studies is a negative correlation with obesity, insulin, and glucose management." (PMID 35805168, 2022). "Here we report that lack of microglial insulin signaling in obesity impaired insulin sensitivity in female mice, which suggests a protective role of intact microglial InsR function in obese females." (PMID 35328354, 2022). "In vivo insulin infusion rapidly suppressed C-peptide levels in healthy men, but not those with obesity and presumably global insulin resistance." (PMID 35136059, 2022). "Sphingomyelins are the most abundant sphingolipids circulating in lipoproteins and, while they are positively related to obesity and waist circumference, they are not correlated to insulin sensitivity in cross-sectional human studies." (PMID 36030929, 2022). "Not surprisingly, iNOS-induced nitrosative stress of the insulin-signaling pathway has emerged as a potent modulator of insulin resistance in obesity." (PMID 35543703, 2022). "Selenite supplementation during adolescence favored adipogenesis by promoting insulin secretion and sensitivity leading to a general anabolism, without obesity or inflammation, in which the adipokine LCN2 played a pivotal role." (PMID 36079831, 2022). "Differences were obtained between patients without obesity and stable plaques and without obesity and unstable plaques for glucagon (p = 0.040), insulin (p = 0.011)." (PMID 36013196, 2022). "Obesity usually leads to IR, Some studies have shown that altered secretion of cytokines in obesity such as TNF-α, IL-6, and leptin induce IR in obesity, while adiponectin stimulates insulin sensitivity." (PMID 36451420, 2022). "In mice, maternal insulin injections in late pregnancy result in obesity in male but not female offspring." (PMID 35258482, 2022). "Women with obesity had markedly higher values of insulin and HOMA-IR than women without obesity, regardless of muscle mass." (PMID 36490255, 2022). "Here we identify insulin expression in the hindbrain's dorsal vagal complex (DVC), and determine the role of this source of insulin in feeding and metabolism, as well as its response to diet-induced obesity in mice." (PMID 36244663, 2022). "To further establish whether ACSS3 level is correlated to obesity and T2D, we retrieved data from published studies, in which ACSS3 expressions in WAT from lean and obese patients, as well as insulin sensitive and insulin‐resistant patients are available." (PMID 35184387, 2022). "The enzyme was identified as a negative modulator of insulin secretion and regulator of energy metabolism affecting the pathogenesis of obesity and metabolic syndrome." (PMID 36005632, 2022). "In the case of our study, cases had higher rates of obesity, were using more drugs for T2DM, had more insulin use and also statin, and had also higher glycated hemoglobin, which might contribute to both infections and hepatic events." (PMID 36093073, 2022). "Leptin, fasting insulin, and ISI did not have significant genetic associations with endometriosis, PCOS, or UF after adjustment for obesity traits, nor did they have any associations with the obesity traits themselves." (PMID 35104295, 2022).
Obesity (continued). "Obesity can lead to the onset of T2D when pancreatic β-cells are no longer able to compensate higher insulin secretion for the reduced insulin sensitivity that often accompanies obesity." (PMID 35931683, 2022). "Typical obesity-associated mediators such as high SFA, glucose or insulin do not directly change S100A9 expression in keratinocytes and the dWAT." (PMID 35198063, 2022). "More broadly, these data suggest that G6PC2 could be a potential target for enhancing insulin secretion as well as lowering FBG in individuals with prediabetes, type 2 diabetes (T2D) and obesity." (PMID 35176280, 2022). "Taken together, our results revealed that all high dietary fatty acid diets induced obesity accompanied by lipid disorders, intestinal barrier dysfunction, and changes in secreted cytokines from gut-brain axis including BDNF, 5-HT, leptin, insulin, and ghrelin." (PMID 35739547, 2022). "People with obesity have an impairment in the ability of insulin to suppress GNG but often have normal basal and postprandial hepatic glucose production rates because of increased insulin secretion." (PMID 36079070, 2022). "CTPG treatment not only reduced fat mass and size of adipose tissue and hepatic steatosis in obese mice, but also effectively improved blood glucose, lipid and insulin tolerance levels, suggesting that CTPG improved obesity, glucolipid metabolism and IR in obese mice." (PMID 36229811, 2022). "The increased insulin, glucose, and HOMA-IR of the High22 group mirrors the obesity-driven phenotype of HFD mice, whereas the presence of hepatic steatosis without major alterations in glucose and lipid metabolism in the Low22 group is similar to the phenotype of SAC mice." (PMID 36611962, 2022). "From 2007 to 2018, the use of insulin analogs (p = 0.009) and a higher number of insulin doses (p = 0.007) increased significantly, with no increase in the prevalence of overweight and obesity." (PMID 35549683, 2022). "After an 8-week alternate-day fasting regimen, the fasting glucose of adults with obesity decreased significantly, and the insulin levels in the participants decreased although not significantly." (PMID 35035610, 2022). "This study aims to evaluate differences in treatment modalities including use of insulin and metformin in relation to different degrees of obesity in pregnant women affected by GDM, taking into special consideration dosing regimens of basal insulin and rapid acting formulations." (PMID 35663318, 2022). "During obesity, ILC1 also accumulates in WAT depots, produces IFN-γ, and contributes to the occurrence of tissue and systemic inflammatory processes and impaired insulin signaling, as cell adoptive transfer led to exacerbated metabolic disorder and proinflammatory macrophage polarization." (PMID 36033972, 2022). "CAP modulated the fasting blood glucose and insulin concentrations as well as decreased the levels of proinflammatory cytokines interleukin-1β and interleukin-6 to treat high-fat, or high-sucrose (HFHS) diet-induced obesity." (PMID 36263142, 2022). "The inclusion of fructose further increased food consumption, obesity, and impaired insulin sensitivity, while it did not alter the plasma ALT levels and the degree of steatosis." (PMID 36555433, 2022). "Protein tyrosine phosphatase 1B (PTP1B) is a negative regulator of insulin and leptin receptor sensitivity in multiple tissues through the dephosphorylation of IRS1 and JAK2, respectively, and is a major contributor to obesity precipitated resistance to these hormones in the brain." (PMID 36111295, 2022). "Although mice in which SIRT3 gene is knocked out do not display phenotypic variations, they present altered insulin signaling pathway, along with decreased glucose tolerance, dyslipidemia, liver steatosis, and obesity." (PMID 35409409, 2022). "Moreover, previous publications investigated the relation of dietary insulin index (DII) and dietary insulin load (DIL) with metabolic disorders such as general obesity and MetS." (PMID 36185667, 2022).